PDGFRA (platelet derived growth factor receptor alpha)
Diseases named in the same sentence as PDGFRA in open-access papers (continued):
Sharing a sentence is not in itself a finding about the gene and the disease.
lung fibrosis (16 papers, 2014 to 2026). "This comprehensive methodological approach revealed distinct fates of PDGFRα+ and αSMA+ cells, their association with collagen production, and a compartment-specific contribution to lung fibrosis." (PMID 32023084, 2020). "PDGFRα expression is induced during the fibrotic process leading to proliferation of PDGFRα+ fibroblasts which contribute to pathological myofibroblasts formation during bleomycin-induced pulmonary fibrosis." (PMID 35629326, 2022). "The CD45−/ALDHbr cell population, and especially its CD45−/ALDHbr/PDGFRα+ subpopulation, was significantly reduced in the lung during bleomycin-induced pulmonary fibrosis." (PMID 34425896, 2021). "A key conclusion from the present study is that the biology not only of αSMA+ cells, but also that of PDGFRα+ cells should be incorporated into studies focusing on lung fibrosis." (PMID 32023084, 2020). "Using a binary lineage-tracing approach (Acta2-tdT and Pdgfra-tdT) in two distinct animal models of lung fibrosis (bleomycin and Fra-2 Tg), we show anatomically preferential localization of αSMA- and PDGFRα-expressing cells at baseline and in fibrosis." (PMID 32023084, 2020). "This directed differentiation of fibroblasts into myofibroblasts, as described for Pdgfrα positive cells, is one of the major requirements when studying pulmonary fibrosis." (PMID 33162897, 2020). "The enhanced mitogenic effect of PDGF-BB on normal compared to fibrotic fibroblasts in lung fibrosis models was attributed to the upregulated expression of PDGFRα." (PMID 31511015, 2019). "Chemical inhibitors of PDGFRα/β tyrosine kinase activity can reduce lung fibrosis in a radiation induced fibrosis model." (PMID 30178747, 2018). "The PDGFRα+ cell lineage gives also rise to myofibroblasts during lung fibrosis." (PMID 35629326, 2022). "Since PDGFRα + fibroblasts also contribute to collagen deposition in the bleomycin-induced pulmonary fibrosis model, we also performed double staining of PDGFRα and vimentin, and results showed that Fed treatment decreased the PDGFRα + fibroblasts compared with that in the BLM group." (PMID 34361644, 2021). "The finding of collagen production being not exclusively produced by αSMA+ cells but also by PDGFRα+ cells is in line with a recent study showing that in bleomycin-induced lung fibrosis, PDGFRα+ cells are the main matrix producing fibroblasts while only a subset of αSMA+ cells expressed collagen." (PMID 32023084, 2020). "The high expression of Pdgfrα suggested that these cells may constitute a model to study activation/differentiation of fibroblast cells observed in pulmonary fibrosis." (PMID 33162897, 2020). "As such, it is still unclear whether αSMA+ cells in particular lung niches are derived from PDGFRα+ cells and whether αSMA+ cells are the sole contributor to collagen production in lung fibrosis." (PMID 32023084, 2020). "We utilized a fate-mapping approach to investigate α-smooth muscle actin (αSMA)+ and platelet-derived growth factor receptor α (PDGFRα)+ cells in two lung fibrosis models, complemented by cell type-specific next-generation sequencing and investigations on human lungs." (PMID 32023084, 2020). "Moreover, 4 weeks after bleomycin treatment, there was a marked increase in lung fibrosis in Ctnnb1-knockout mice, as assessed by anti-PDGFRa, anti-PDGFRb, anti-collagen I, and anti-collagen IV immunofluorescence staining and Sirius red staining of lung sections." (PMID 41535251, 2026). "Similar to the CD45−/ALDHbr/PDGFRα+ population in the current study, CD45− lung SP cells have been reported to express mesenchymal markers and exhibit MSC properties, and have been shown to be decreased in BLM-induced pulmonary fibrosis." (PMID 34425896, 2021).
thyroid cancer (15 papers, 2009 to 2025). "Overexpression of PDGFRA is strongly linked to radioiodine resistance and distant metastasis in human thyroid cancer, particularly radiorefractory thyroid cancer (RAIR-TC)." (PMID 39850565, 2024). "In the present study, we confirmed the association between PDGFRA and radioiodine resistance in thyroid cancer using bioinformatics analysis and constructed a prediction model of PDGFRA inhibitors using machine learning and molecular docking approaches." (PMID 35645805, 2022). "The overexpression of PDGFRA is closely associated with radioiodine resistance and distant metastasis in human thyroid cancer." (PMID 35645805, 2022). "Aberrant activation of platelet-derived growth factor receptor α (PDGFRA) has been implicated in tumorigenesis and radioiodine resistance of thyroid cancer, indicating its therapeutic potential." (PMID 35645805, 2022). "In the current study, we applied the bioinformatics approach to demonstrate the correlation between PDGFRA and radioiodine resistance in thyroid cancer and created a molecular docking and molecular dynamic simulation model of PDGFRA inhibitors." (PMID 39850565, 2024). "Inhibiting platelet-derived growth factor receptor alpha (PDGFRA) enhanced radioiodine sensitivity in thyroid cancer." (PMID 38259849, 2023). "Platelet-derived growth factor receptor-α (PDGFRA) is a proangiogenic factor that regulates tumor growth and metastasis and is highly expressed in thyroid cancer, correlating with poor survival." (PMID 35159110, 2022). "In summary, PDGFRA plays an important role in the uptake or transport of radioiodine in thyroid cancer and is a reliable target for reversing RAIR-TC radioiodine resistance." (PMID 35645805, 2022). "Gene editing of PDGFRA with CRISPR/Cas9 in aggressive thyroid cancer cells blunted PDGFRA expression, reduced cell invasion and reversed EMT genes expression (reduced VIM, SLUG, and N-Cadherin and induced E-cadherin)." (PMID 35159110, 2022). "The expression of PDGFRA in ATC is significantly higher than that in normal thyroid cells, which confirmed that the expression of PDGFRA in RAIR-TC is higher than that in normal thyroid or radioiodine-sensitive thyroid cancer." (PMID 35645805, 2022). "Recently, PDGFA and PDGFRA were reported up-regulated in thyroid carcinoma cell lines and autocrine activation of PDGFRA was suggested to play a crucial role in the carcinogenesis of thyroid cells." (PMID 19968886, 2009). "PDGFRA expression boosts thyroid cancer cell proliferation and metastasis." (PMID 39850565, 2024). "Moreover, PDGFRA gene editing reduced spontaneous metastasis to the lung when injected in immunocompromised mice, indicating a beneficial role for PDGFRA inhibitors, such as imatinib to treat aggressive thyroid cancer." (PMID 35159110, 2022). "On the other hand, PDGFRA can cause cytoskeletal rearrangement, increasing migration potential, the formation of invasive pseudopodia, and EMT-mediated lymphatic metastasis in thyroid cancer cells." (PMID 31126066, 2019). "In terms of thyroid cancer, there were two predicted target genes: PDGFRA, functioning as a tumor progression promoter, and CD47, which may influence the radiation reaction of thyroid cell." (PMID 25405731, 2014). "In addition, PDGFA and PDGFRA were recently reported overexpressed in two thyroid carcinoma cell lines, one derived from PTC, the other from FTC." (PMID 19968886, 2009). "Among twelve predicted genes, PDGFRA and CD47 had been studied in thyroid cancer." (PMID 25405731, 2014).
colon carcinoma (13 papers, 2007 to 2024). "Our results underscore the novel role of lncXIST in promoting M2-like macrophage polarization via the miR-17-5a/PDGFRA axis as well as its potential as both a diagnostic biomarker and a therapeutic target for colon cancer." (PMID 39518984, 2024). "In this study, we investigated the molecular mechanism of colon cancer-derived exosomes and showed that lncXIST is able to mediate M2 macrophage polarization by regulating miR-17-5p and PDGFRA." (PMID 39518984, 2024). "Taken together, this evidence implies that miR-34a has a suppressive effect on colon cancer through the regulation of PDGFRA." (PMID 38725047, 2024). "Altogether, the results from this study demonstrated that exosomal lncXIST can induce macrophage M2 polarization by regulating the miR-17-5p/PDGFRA axis to promote colon cancer progression." (PMID 39518984, 2024). "Forwarding tests, involving Western blotting and quantitative reverse-transcription polymerase chain reaction analysis provided further evidence that miR-34a was instrumental in cutting the expression of PDGFRA in colon cancer cells." (PMID 38725047, 2024). "Altogether, our data suggest that lncXIST from colon cancer-derived exosomes promotes PDGFRA expression by inhibiting miR-17-5p." (PMID 39518984, 2024). "Functional assays verified that miR-34a exerted an inhibitory action on colon cancer by targeting PDGFRA." (PMID 38725047, 2024). "Furthermore, our findings showed that colon cancer-derived exosomes secreted lncXIST to sponge miR-17-5p, which, in turn, promoted the expression of PDGFRA, a common gene found in all three signaling pathways, to facilitate M2-like macrophage polarization." (PMID 39518984, 2024). "PDGFRα was reported as highly expressed in CMS4 colon tumors." (PMID 33213472, 2020). "PDGFRA in particular is also known to be significantly down-regulated in colon cancer." (PMID 22558171, 2012). "To follow up on our previous finding of PDGF overexpression in CRC, we analyzed the expression of its corresponding receptors, PDGFRα and PDGFRβ, and presumed cross-binding partners, VEGFR1 and VEGFR2, in primary human colon cancer tissue samples (n = 42)." (PMID 36264073, 2022). "Given the observed overexpression of PDGF/VEGF receptors in human colon cancer tumors, we analyzed several CRC cell lines for the expression of PDGFRα, PDGFRβ, VEGFR1, and VEGFR2." (PMID 36264073, 2022). "As shown, in both HT-29 cells and primary human colon cancer cells (“pri-Can-1”), NINJ2 co-immunoprecipitated with EGFR, PDGFRα, PDGFRβ and FGFR." (PMID 31597121, 2019). "NINJ2 co-immunoprecipitated with multiple RTKs (EGFR, PDGFRα/β and FGFR) in CRC cells and human colon cancer tissues." (PMID 31597121, 2019). "Related studies have found that the HCMV signaling pathway can induce the activation of platelet-derived growth factor receptor α (PDGFRα) and PI3K/AKT in colon cancer cells, thereby promoting the proliferation of cancer cells and enhancing their migration ability." (PMID 34194533, 2021).
malignant glioma (13 papers, 2009 to 2024). A grade III or grade IV glioma arising from the central nervous system. "Recently, also in pediatric high-grade gliomas, ligand-independent and tumorigenic in-frame PDGFRA deletion variants have been reported." (PMID 25862637, 2015). "We have generated a mouse model of malignant glioma based on knock-in of a mutant PDGF receptor α (PDGFRα) that is expressed in oligodendrocyte precursor cells (OPCs) after activation by a Cre recombinase." (PMID 25683249, 2015). "Using phospho-proteomics in a new model of malignant glioma, we reveal that clinically relevant, chronic PDGFRα signaling differs considerably from acute receptor stimulation and unveils previously unrecognized control over key elements of the translation initiation machinery." (PMID 30456354, 2018). "Furthermore, the ablation of SULF2 decreases tumor growth, prolongs host survival and decreases the activity of PDGFRα, as well as related downstream signaling pathways in human and mouse malignant gliomas." (PMID 26248280, 2015). "PDGFRA amplification is important for subgroup classification of malignant gliomas." (PMID 25364409, 2014). "The results of the current study indicate that ribavirin may present as a novel agent for malignant glioma chemotherapy and that PDGFRA expression levels may be a significant marker of the antitumor efficacy of ribavirin against malignant gliomas." (PMID 25364409, 2014). "One study analysed the prevalence of PDGFRA mutations in patients enrolled in a phase I/II study of imatinib mesylate in recurrent malignant gliomas; however, no activating mutations were observed." (PMID 19707201, 2009). "Our analysis identified PDGFRA and PDGFA—both of which are findings from our investigation—as key genes significantly enriched in pathways that are critical for malignant glioma processes." (PMID 39606019, 2024). "In our study, by activating a mutant PDGFRα cell-autonomously in the OPC population, we provide direct evidence for OPC as a cell of origin for malignant glioma." (PMID 25683249, 2015).
systemic mastocytosis (13 papers, 2009 to 2023). Systemic mastocytosis (SM) comprises a heterogeneous group of rare acquired and chronic hematological malignancies that are related to an abnormal proliferation of mast cells in tissue, including bone marrow, with or without skin involvement. "PDGFRA rearrangements (mostly FIP1L1-PDGFRA fusions) are found in 10–20% of patients with idiopathic hypereosinophilia and in some cases of systemic mastocytosis." (PMID 34716856, 2022).
bladder cancer (12 papers, 2011 to 2025). "Again, PDGFRA gene expression which usually mutates in bladder cancer may foretell a worse prognosis as well." (PMID 39678505, 2024). "PDGFRα+ ITGA11+ CAFs are associated with lymphovascular invasion (LVI) and early metastasis in early-stage bladder cancer, promoting lymphangiogenesis by recognizing the ITGA11 receptor SELE on lymphatic endothelial cells." (PMID 40766310, 2025). "PDGFRα+ITGA11+ CAFs are correlated with lympho-vascular invasion in bladder cancer, and these CAFs promote lympho-vascular invasion and lymphatic metastasis in bladder cancer." (PMID 39726782, 2024). "Guo L, Gao Z, and others also support the high correlation between PDGFRA and the prognosis of patients with bladder cancer." (PMID 37880682, 2023). "Similarly, our differential gene expression analysis of bladder cancer fibroblast subtypes identified PDGFRA as a marker specifically in iCAFs." (PMID 41214597, 2025). "Not only EGFR and PDGFRA, but other novel biomarkers are receiving recognition for bladder cancer." (PMID 39678505, 2024). "Male-specific hub genes, including DAXX, IKBKB, PDGFRA, and PPARG, showed significant correlations with immune cell types, highlighting a distinct immune microenvironment in male bladder cancer." (PMID 40458476, 2025). "Further, CHI3L1 from PDGFRα+ITGA11+ CAFs aligns the surrounding matrix to promote tumor cell intravasation, promoting lympho-vascular invasion and lymphatic metastasis of bladder cancer." (PMID 39726782, 2024).
gastric tumors (12 papers, 2010 to 2024). "PDGFRA mutations (present in 10 % of primary GISTs) are common in tumors of the stomach and have epithelioid features as well as indolent behaviors." (PMID 26276366, 2016). "On the other hand, GISTs with PDGFRA exon 18 mutations are predominantly gastric tumors with an epithelioid morphology." (PMID 20598160, 2010). "In addition to the relative paucity of aberrations in GISTs with PDGFRA mutations seen in the present study, the finding of a lower incidence of 22q losses in gastric tumors with this genotype was also in accordance with published data." (PMID 35284037, 2022). "Moreover, KIT-mutated gastric GISTs featured an inferior degree of infiltration both when compared with PDGFRA-mutated gastric tumors and when compared with the KIT-mutated counterpart of the intestine." (PMID 33048845, 2020). "Thus a gastric tumor composed of epithelioid cells often harbors a PDGFRA exon 18 mutation." (PMID 37488222, 2023). "And also, KIT/PDGFRA wild-type GISTs had significantly more primary gastric tumors and metastases to the lymph nodes than patients with KIT/PDGFRA-mutated GISTs, which commonly metastasized to the liver and peritoneum." (PMID 39447098, 2024). "Mutations in the gene coding for platelet-derived growth factor receptor alpha (PDGFRA) affect 10% of patients with GIST and are typically associated with stomach tumors." (PMID 35847170, 2022). "A trend for enrichment of immunity-related genes also emerged when contrasting PDGFRA versus KIT gastric tumors and overt GISTs versus miniGISTs." (PMID 33048845, 2020). "PDGFRA mutations are generally associated with a more favorable outcome, occurring in gastric tumors with low or no malignant potential." (PMID 39199677, 2024). "It is of interest that in our series, none of the gastric tumors with either the double loss -14 and -22 as the only change, or this change in the basic clone, carried PDGFRA mutations." (PMID 35284037, 2022). "GISTs that occur in children are a separate clinicopathologic and molecular subset with predilection for girls, multifocal gastric tumors, and wild-type KIT/PDGFRA genotype." (PMID 25264210, 2014). "Since no PDGFRA mutations were identified in non-gastric GISTs in this study, and to avoid any site-specific effect in KIT-mutated tumors, only gastric tumors were compared." (PMID 35284037, 2022).
liver cancer (12 papers, 2011 to 2025). An epithelial or non-epithelial malignant neoplasm that arises from the liver. "Collectively, these findings suggest that elevated PDGFRA expression in liver cancer tissues is associated with reduced sensitivity to lenvatinib therapy, underscoring the potential of PDGFRA expression as a predictive biomarker for the therapeutic response to lenvatinib in HCC patients." (PMID 40336047, 2025). "Therefore, we identified an inflammatory cancer-associated fibroblast (iCAF) subcluster (PDGFRA+CAFs) that originates from HPCs differentiation in both rat models and human liver cancer, suggesting it is a critical subcluster influencing liver cancer progression." (PMID 41408647, 2025). "We further analysed HCC clinical data to understand the clinical relevance of PDGFRα+ CAFs in relation to liver cancer patients." (PMID 39827226, 2025). "Both univariate and multivariate Cox regression analyses identified PDGFRA H-score as an independent prognostic factor for relapse-free and overall survival in liver cancer patients." (PMID 40336047, 2025). "More importantly, targeting PDGFRA with its selective inhibitor avapritinib, significantly enhanced the sensitivity of liver cancer cells to lenvatinib, a result that has also been verified in patient-derived organoid (PDO) models and patient-derived xenograft (PDX) mouse models." (PMID 40336047, 2025). "Targeting the cancer-specific ectopic phosphorylation sites of PDGFRA induced by MAN2A1-FER may hold promise as an effective treatment for liver cancer." (PMID 39082961, 2024). "Furthermore, we have corroborated the correlation between PDGFRA levels and treatment response in lenvatinib-treated liver cancer patients through patient biopsy samples, proposing that the targeting of PDGFRA could represent an efficacious strategy to surmount lenvatinib resistance." (PMID 40336047, 2025). "In clinical practice, several makers of liver cancer, such as VEGFR1, FGFR1 and PDGFRα, were identified and their potentials as a therapeutic target were explored." (PMID 38192337, 2023). "On the other hands, excessive activation of PDGFRα signaling in PDGF-C transgenic mice resulted in liver cirrhosis by 9 months, and interestingly, these mice with cirrhosis develop liver cancer in the later stage, resembling human HCC with background liver cirrhosis." (PMID 28465473, 2017).